CT47A1 (cancer/testis antigen family 47 member A1)
Synonyms: CT47.1
Gene: Protein-coding gene on chromosome X (120,982,476 to 120,985,760, reverse strand). Ensembl gene ENSG00000236371.
Subcellular location (Human Protein Atlas): Nucleoli
Homologues: Orthologues: macaque CT47B1 (77% identical). Paralogues in human: CT47A10 (100% identical), CT47A11 (100% identical), CT47A12 (100% identical), CT47A2 (100% identical), CT47A3 (100% identical), CT47A4 (100% identical), CT47A5 (100% identical), CT47A6 (100% identical), CT47A7 (100% identical), CT47A8 (100% identical), CT47A9 (100% identical), CT47B1 (86% identical), and 1 more.
Diseases named in the same sentence as CT47A1 in open-access papers:
CT47A1 is named in the same sentence as 2 diseases in open-access papers, as found by Europe PMC text mining. Sharing a sentence is not in itself a finding about the gene and the disease. The quoted sentences say what the papers report.
tumor (1 paper, 2021). "CT47A1, PAGE1, MAGEA9, MAGEC2, and MAGEA1 were detected at protein level in tumor tissues (CT47A1 in 14%, PAGE1 in 23%, MAGEA9 in 11%, MAGEC2 in 59% and MAGEA1 in 34% of tumors)." (PMID 34065388, 2021).
CT47A1 also shares sentences with these, for which no sentence is quoted: ductal carcinoma in situ (1 paper).